TTR (transthyretin)
Diseases named in the same sentence as TTR in open-access papers (continued):
Sharing a sentence is not in itself a finding about the gene and the disease.
neuropathy (continued). "The phase 3, open-label, clinical trial for ATTRv patients with PN, NEURO-TTRansform trial, compared eplontersen with the placebo cohort of the NEURO-TTR trial, showing a significantly lowered serum TTR concentration, less neuropathy impairment and better QoL." (PMID 40429476, 2025). "Eplontersen is a novel ASO formulation that reduced serum TTR, lessened neuropathy impairment, and improved quality of life compared to a historical placebo in ATTRv polyneuropathy patients in the phase 3 NEURO‐TTRansform trial." (PMID 39576264, 2025). "For reliable diagnosis of TTR neuropathy, easily accessible, non-invasive, and sensitive biomarkers for amyloid neuropathy are essential." (PMID 38698025, 2024). "In the current work, we demonstrate the unique binding features of the anti-misTTR Ab-A and corroborate these characteristics with the protective properties that are observed in a series of in vitro studies and in a model of inducible TTR neuropathy." (PMID 36290413, 2022). "Neurological manifestations including signs of neuropathy and dysautonomia due to amyloid damage of small myelinated and unmyelinated fibres are frequently reported in patients with transthyretin CA." (PMID 36338485, 2022). "Ab-A protects neurons from oligomeric TTR-inducible toxicity and enhances the uptake of aggregated TTR by microglia, leading to the attenuation of motoric deficit in a model of neuropathy produced by the sciatic infiltration of human-derived TTR amyloid." (PMID 36290413, 2022). "These two complementary protective mechanisms are evident by the ability of the antibody to protect from experimental neuropathy inducible by misfolded TTR infiltrated into the sciatic nerves of rats." (PMID 36290413, 2022). "In a series of 15 patients with TTR-FAP a reduction in corneal nerve fiber length was related to the neuropathy impairment score of the lower limbs, autonomic dysfunction, sensory nerve action potential and IENFD." (PMID 35295436, 2021). "Nevertheless, by accessing the specific EUGT numbers, we have investigated this aspect for a few diseases (SMN, DMD, LGMDs, Pompe disease and TTR related neuropathy)." (PMID 32946487, 2020). "Inotersen and patisiran substantially reduce the amyloidogenic precursor protein transthyretin and have demonstrated efficacy in patients with early‐ and late‐stage disease and in slowing or improving neuropathy progression." (PMID 31368669, 2019). "Liver transplantation provides a useful and specific therapy for TTR-FAP by allowing for the suppression of the main source of the mutant TTR; it prevents neuropathy progression in approximately 70% of cases with Val30Met mutation on a long-term basis." (PMID 24572009, 2014). "Transthyretin is a tetrameric transport protein whose monomers, when destabilized, can misfold and form amyloid fibrils, leading to serious diseases like transthyretin amyloidosis cardiomyopathy and neuropathy." (PMID 41513988, 2026). "Change from baseline in the NEURO-TTRansform primary endpoints of serum transthyretin (TTR) levels to Week 65, modified Neuropathy Impairment Score +7 (mNIS+7) composite score to Week 66, and Norfolk Quality of Life-Diabetic Neuropathy (Norfolk QoL-DN) total score to Week 66 were evaluated." (PMID 41937511, 2026). "TTR mutations have previously been identified in patients with neuropathy without a definite etiology, although these patients also had atypical features." (PMID 37266816, 2023). "Herein, we tested the hypothesis that a monoclonal antibody targeting the soluble oligomeric as well as the aggregated TTR would influence experimental neuropathy." (PMID 36290413, 2022). "Thus, the monoclonal antibody targeting soluble and aggregated TTR is effective in experimental neuropathy, likely due its ability to act as a neuroprotective agent, as well its misTTR-mediated clearance via microglia." (PMID 36290413, 2022).
neuropathy (continued). "In contrast, the burden of noncardiac phenotypes was no different from the rest of the population, and the odds of multisystem diagnoses (cardiac and neuropathy/ophthalmological/miscellaneous) were not different based on TTR variant status." (PMID 34746851, 2021). "The results from our Canadian sample suggest that routine genetic screening for the TTR gene in all patients with neuropathy of unknown etiology is likely to be of low yield in North America." (PMID 32493526, 2020). "In the last few years, the TTR gene has been added to most neuropathy genetic test panels." (PMID 32493526, 2020). "However, late-onset patients are not eligible for liver transplantation because the progression of cardiomyopathy and neuropathy continues, probably due to wild-type TTR deposition." (PMID 30764529, 2019). "The next step is to identify a better control group, that is, patients with neuropathy of unknown origin with the same biographic characteristics to refine the results of our study and foster the early diagnosis and treatment of TTR‐FAP." (PMID 29568686, 2018). "In this sense, profiling biomarkers in the blood of patients is most useful and may allow diagnosis, prognosis, or analysis of therapeutic efficacy and progression of TTR neuropathy." (PMID 28583160, 2017). "Patients with TTR-FAP may experience very different patterns of neuropathies which pose a challenge for diagnosis." (PMID 27212199, 2016). "Another common variant, at least among African-Americans (and found amongst West Africans), is the TTR V122I variant which was detected in the heterozygous state in 4% of African-Americans and is associated with hypertrophic restrictive cardiomyopathy in older individuals, but without neuropathy." (PMID 35331287, 2022). "Transthyretin familial amyloid polyneuropathy (TTR-FAP) is a fatal inherited disorder characterized by pain, numbness and weakness due to a progressive neuropathy." (PMID 35295436, 2021). "The typical phenotype of TTR-FAP is severe progressive sensory and motor neuropathy with autonomic neuropathy among adults, and most of them with cardiomyopathy." (PMID 33716932, 2021). "There are many examples in the literature that the deposition of both ordered (e.g. transthyretin, TTR) and disordered (e.g. β-amyloid) protein aggregates contribute to neuropathy, nephropathy, and cardiomyopathy." (PMID 32968182, 2020). "A97S is the predominant genotype of Taiwanese TTR‐FAP patients, presenting by a unique phenotype composed of a late‐onset but rapid‐progressive neuropathy and life‐threatening cardiopathy." (PMID 31502419, 2019). "TTR produced in the liver is responsible for the major manifestations of ATTR amyloidosis, such as neuropathy and cardiomyopathy." (PMID 30764529, 2019). "Treatment with tafamidis was initiated after TTR-FAP was diagnosed, but our patient’s neuropathy was aggravated nonetheless." (PMID 25471118, 2014). "Interpretation: TTR-FAP patients had milder nerve enlargement with less variability in CSAs of median nerves than those with CIDP, suggesting that nerve ultrasound can be a potential useful auxiliary tool to help differentiate the two neuropathies." (PMID 33716932, 2021). "In FAP, neuropathy begins at the earliest stages of the disease when nonfibrillar TTR deposits in the PNS." (PMID 24459092, 2014). "In conclusion, our study showed TTR-FAP patients had milder nerve enlargement with less variability in CSAs of median nerves than their CIDP counterparts, suggesting that nerve ultrasound is a potential useful auxiliary tool in differentiating the two neuropathies." (PMID 33716932, 2021). "Indeed, TTR immunostaining-positive but Congo red-negative nonfibrillar precursors of amyloid (i.e., TTR oligomers) have been found in the endoneurium of ATTRv amyloidosis patients, even in the early stage of neuropathy." (PMID 30764529, 2019).
neuropathy (continued). "Moreover, transthyretin protein silencers such as patisiran and inotersen have shown promising outcomes in the treatment of ATTR-CA and are currently approved by the American Food and Drug Administration (FDA) for the treatment of hereditary ATTR with concurrent neuropathy." (PMID 37953763, 2023). "In contrast to hATTRv, a subtype of FAP where neuropathy is frequent, neuropathy is either not frequent or underdiagnosed in SSA, suggesting that mutant TTR is more neurotoxic than wtTTR." (PMID 32604774, 2020). "Moreover, post-mortem studies were able to demonstrate TTR amyloid deposition regardless of the type of ATTR in almost all organs and tissues of affected persons Therefore, patients with ATTR may show different patterns of neuropathy." (PMID 35817943, 2023).
systemic amyloidosis (84 papers, 2008 to 2026). "Here, we investigate S52P and L111M transthyretin variants, both causing a severe form of systemic amyloidosis mostly targeting the heart at a relatively young age with heterogeneous phenotype among patients." (PMID 38380705, 2024). "Another type is a hereditary systemic amyloidosis, which is associated with abnormal genetic sequence (variant TTR)." (PMID 39445188, 2024). "A literature search in PubMed, Embase, and Web of Science was performed on 14 February 2024 for studies investigating NfL levels in patients with systemic amyloidosis and transthyretin gene-variant (TTRv) carriers." (PMID 38612579, 2024). "ATTRv is a systemic amyloidosis with autosomal dominant transmission characterized by a genetic mutation of TTR, of which more than 150 variants have been identified, the majority of which are amino acid pathogenic variants due to a nucleotide substitution." (PMID 39451564, 2024). "Hereditary transthyretin amyloidosis is a disease caused by genetic abnormalities in the gene that codes for transthyretin (TTR), resulting in the production of variant TTR and systemic amyloidosis." (PMID 37713404, 2023). "Senile systemic amyloidosis, a disease of elderly is caused by amyloid deposition of wild-type transthyretin." (PMID 33907095, 2021). "Systemic amyloidosis of the ATTR is one of the most abundant forms of systemic amyloidosis and caused by misfolding of the circulating blood protein transthyretin (TTR)." (PMID 31676763, 2019). "Recently, a new familial form of human prion disease defined as PrP systemic amyloidosis has been reported to show clinical overlap with familial amyloid polyneuropathy, which is known to be associated with TTR mutations." (PMID 29593496, 2018). "Other major forms of systemic amyloidosis are associated with the deposition of transthyretin, either wild-type (WT) (wtATTR) or mutant forms (ATTR), leukocyte chemotactic factor 2 (Alect2), and the acute phase protein serum amyloid protein A (AA)." (PMID 28928748, 2017). "The most common forms of systemic amyloidosis, such as those caused by immunoglobulin light chains, TTR, lysozyme, and lipoproteins, are prototypic examples of instances when the sites of production and of major deposition are totally different." (PMID 25750126, 2015). "FAP is the most prevalent systemic amyloidosis and is caused by the deposition of TTR variants, mainly in peripheral nerves." (PMID 23466880, 2013). "Cardiac involvement is frequent in systemic amyloidosis of immunoglobulin light chain (AL) and transthyretin (TTR) types, is associated with a poor prognosis, and can have therapeutic implications." (PMID 19032744, 2008). "Moreover, we identified strong interactions between transthyretin (TTR) oligomers—another well-characterized amyloid protein associated with systemic amyloidosis—and the LILRB2 and LILRB5 receptors." (PMID 41233352, 2025). "It remains unclear whether myocardial signal alterations or cardiac functional changes at CMR in asymptomatic carriers of pathogenic TTR mutations precede overt clinical signs of systemic amyloidosis." (PMID 40422943, 2025). "One protein that can cause systemic amyloidosis is transthyretin (TTR), a homotetrameric protein acting as a transport protein in plasma, that may have other less investigated functions in other parts of the body as well." (PMID 35358243, 2022). "ATTR can result either from slow deposition of amyloid fibrils derived from wild‐type (non‐mutant) TTR in the elderly (senile systemic amyloidosis) or when mutations in the TTR gene encode variant protein, decreasing the stability of the TTR tetramer and promoting misfolding into amyloid fibrils." (PMID 35567784, 2022). "ATTRv is a fatal systemic amyloidosis caused by mutations in the transthyretin (TTR) gene." (PMID 35317351, 2022).
systemic amyloidosis (continued). "Imaging tools such as MRI of the roots and nerves could contribute to the diagnosis of immune-mediated neuropathies, hereditary transthyretin (TTR) associated systemic amyloidosis and others in the recent past." (PMID 33572591, 2021). "Alternatively, systemic amyloidosis may develop because of an inherited mutation of the TTR gene (hATTR) or another less common genetic mutation." (PMID 34106429, 2021). "Translation of the p5+14 peptide as a clinical imaging agent for patients with AL and transthyretin-associated systemic amyloidosis is currently being supported by the Science Moving towArds Research Translation and Therapy (SMARTT) Program at the National Heart, Lung and Blood Institute of the NIH." (PMID 26936002, 2016). "Indeed, TTR, carrier of the thyroid hormone thyroxine (T4) in serum and CSF, is associated with systemic amyloidosis in humans, but also with an anti-amyloidogenic effect preventing Aβ deposition in neuronal cell cultures." (PMID 24898206, 2014). "TTR is one of the 27 human proteins known to be associated with local or systemic amyloidosis." (PMID 21179560, 2010). "Systemic amyloidosis is categorized by precursor protein, and the most common are immunoglobulin light-chain amyloidosis (AL) and transthyretin (TTR) protein produced predominantly in the liver (ATTR amyloidosis)." (PMID 41362673, 2026). "Examples include α-syn in PD, tau and amyloid beta (Aβ) in AD, TAR DNA-binding protein 43 in amyotrophic lateral sclerosis (ALS), Huntingtin protein in Huntington’s disease (HD), and transthyretin (TTR) in systemic amyloidosis." (PMID 40534869, 2025). "Systemic amyloidosis predominantly involves disordered light chain immunoglobulin, transthyretin or serum amyloid A." (PMID 41583176, 2025). "Transthyretin (TTR), a serum protein synthesized mainly in the liver, causes two types of systemic amyloidosis." (PMID 39445188, 2024). "The vast majority of the patients have either light chain (AL) or transthyretin (ATTR) systemic amyloidosis in the background." (PMID 35885070, 2022). "Transthyretin (TTR) and β2-microglobulin (β2-m) both lead to systemic amyloidosis by forming amyloid depositions in different organs throughout the body." (PMID 33244624, 2021). "Systemic amyloidosis (which can be of the senile type or an early-onset familial type) is the result of the deposition of transthyretin (TTR) protein." (PMID 33123145, 2020). "Senile systemic amyloidosis is a late onset disease in which wild-type (WT) TTR aggregates, weakening the heart muscle." (PMID 26459562, 2015). "The other type is senile systemic amyloidosis (SSA), which is an aging-related sporadic systemic amyloidosis that is induced by wild-type (WT) TTR." (PMID 25228988, 2014). "TTR has, however, an inherent propensity to assemble into insoluble amyloid fibrils, which sporadically leads to senile systemic amyloidosis (SSA) with deposits of wild-type TTR (TTRwt) mainly in the cardiac tissue late in life." (PMID 21179560, 2010). "Notably, transthyretin (TTR) exhibited the highest importance score, implicating its role in neurodegenerative diseases and systemic amyloidosis." (PMID 40559081, 2025). "Transthyretin amyloid cardiomyopathy (ATTR-CM) is a systemic amyloidosis characterized by misfolding of the transthyretin (TTR) protein, resulting in the formation and deposition of insoluble amyloid fibrils in the interstitial space of the myocardium and other organs." (PMID 41235331, 2025). "In some cases, the protein itself may be intrinsically predisposed to develop a pathological conformation with age, as occurs in patients suffering from senile systemic amyloidosis due to wild-type transthyretin." (PMID 39451564, 2024). "In our opinion, the possibility that therapy with TTR stabilizers or TTR mRNA silencers could delay the onset of systemic amyloidosis in such patients should be evaluated." (PMID 33925301, 2021).
systemic amyloidosis (continued). "More than 130 mutations of the TTR protein have been identified, the majority of which are noted to cause systemic amyloidosis, mainly impacting the peripheral nervous system and the heart." (PMID 34106429, 2021). "Among these, only about 15 TTR variants are reported as non-amyloidogenic, while most TTR point mutations induce systemic amyloidosis with predominant neuropathic, or cardiac phenotypes." (PMID 33362465, 2020). "On the other hand, TTR itself may form aggregates and lead to systemic amyloidosis." (PMID 30615651, 2019). "Indeed, nT1 and ECV values elevation occurs in CA due to interstitial space expansion associated with misfolded TTR protein accumulation and may also be observed in patients with systemic amyloidosis without ventricular hypertrophy or LGE." (PMID 40422943, 2025). "Transthyretin (TTR), a homotetrameric plasma protein synthesized mainly by the liver, gives rise to two types of systemic amyloidosis." (PMID 33274477, 2021). "Evaluation for systemic amyloidosis, including immunohistochemistry for A amyloid (AA), transthyretin (TTR) amyloid and serum free light chains, were negative and non‐immunospecific." (PMID 41063788, 2025). "The proband 4 patient with senile systemic amyloidosis and the proband 5 patient with TTR showed non-typical HCM pattern with transmural LGE." (PMID 34362124, 2021). "SSA, in which WT TTR forms amyloid deposits in various tissues, is an age-related nonhereditary systemic amyloidosis and affects mainly cardiac functions in elderly people." (PMID 25228988, 2014). "Wild type is described as an “age-related, non-hereditary systemic amyloidosis” that is induced by unknown factors to form amyloid deposits by wild type TTR proteins." (PMID 33203794, 2020).